BMP4 (bone morphogenetic protein 4)
Diseases named in the same sentence as BMP4 in open-access papers (continued):
Sharing a sentence is not in itself a finding about the gene and the disease.
osteoarthritis (6 papers, 2012 to 2025). A noninflammatory degenerative joint disease occurring chiefly in older persons, characterized by degeneration of the articular cartilage, hypertrophy of bone at the margins and changes in the synovial membrane. "Our results also highlighted that only three central genes—Prdx1, Nfkb1, and Bmp4—were differentially expressed during Mia-induced osteoarthritis, demonstrating a limited overlap in DEGs related to Mia-induced OA." (PMID 40722985, 2025). "Previously, we have shown that murine MDSCs can efficiently repair rat MIA-induced osteoarthritis when transduced with retroviral-BMP4/GFP." (PMID 31771623, 2019). "It has been shown that murine MDSCs transduced with BMP4/GFP can directly differentiate into chondrocytes in MIA-induced osteoarthritis and osteochondral defects, but also in a small percentage compared to those from host cells." (PMID 31771623, 2019). "BMP4 and BMP5 are downregulated in osteoarthritis, rheumatoid arthritis, and systemic lupus erythematous." (PMID 32139667, 2020). "Two patients with arthritis (one with PsA and one with RA) and two with osteoarthritis were excluded because their IHC readings of BMP4 and Wnt5b could not be performed correctly." (PMID 38672170, 2024).
pituitary adenomas (6 papers, 2011 to 2020). "Bone morphogenetic protein-4 (BMP-4) has been proposed as both an oncogene and a tumor suppressor gene in pituitary adenomas Reduced BMP-4 expression is associated with epigenetic changes, which are reversed in AtT-20 and GH3 cell lines incubated with the epidrugs zebualarine and TSA." (PMID 32012988, 2020). "BMP4 is up-modulated in pituitary adenomas in both mice and humans and acts via SMAD4 to up-regulate c-myc, with signalling mechanisms overlapping with the estrogen receptor." (PMID 23226476, 2012). "Previous microarray studies of human pituitary adenomas have detected many novel candidate genes, including PTTG, GADD45, MEG3a, and BMP-4." (PMID 25642247, 2015). "The role of BMP2, BMP4 and BMP7 as signalling peptides in the programming of pituitary development makes them plausible candidates for pituitary disorders including congenital insufficiency as well as pituitary adenomas." (PMID 24289245, 2013).
pulmonary arterial hypertension (6 papers, 2014 to 2024). Pulmonary arterial hypertension (PAH) is a group of diseases characterized by mean pulmonary artery pressure >20 mmHg and elevated pulmonary arterial resistance leading to right heart failure. "Furthermore, the regulation of the PI3K/AKT pathway by BMP4 may be an important mechanism underlying the treatment of pulmonary artery hypertension and provide a novel therapeutic insight for the future." (PMID 25110865, 2014). "L. Dewachter, etc. confirmed that in idiopathic pulmonary hypertension, BMP4 promotes PASMCs mitosis through Smad and p38MAPK pathway." (PMID 25203114, 2014). "Moreover, BMP4 appears to be at the molecular basis of certain lung diseases such as pulmonary arterial hypertension (PAH), chronic obstructive pulmonary disease (COPD) or hypoxic pulmonary hypertension." (PMID 32316263, 2020). "Bone morphogenetic protein-4 (BMP4), a member of the transforming growth factor β (TGF-β) family of growth factors, is activated and increased under hypoxic conditions, which plays an important role in the progression of pulmonary arterial hypertension (PAH)." (PMID 25110865, 2014).
teratoma (6 papers, 2011 to 2017). A non-seminomatous germ cell tumor characterized by the presence of various tissues which correspond to the different germinal layers (endoderm, mesoderm, and ectoderm). "While a single differentiation strategy is accepted, it is possible that other differentiation methods (culturing in vitro on Matrigel, BMP4 or in vivo with teratoma formation) would have obtained different results." (PMID 25723476, 2015). "Mouse ESCs maintained under serum-free conditions supplemented with LIF, Bmp4, N2 and B27 are pluripotent and can contribute to the germline in chimeric animals, and grew into teratomas." (PMID 21731714, 2011). "In contrast, mESCs cultured in CDSF with Bmp4 or the Gsk3β inhibitor maintained Oct3/4 expression, increased the number of cell doublings and formed teratomas in 17% or 67% of transplantations by 7 months, respectively." (PMID 21731714, 2011). "However, upon LIF/BMP4 stimulation, FABS cells up-regulated E-cadherin and showed improved chimerism ability and teratoma formation." (PMID 21779327, 2011).
tooth agenesis (6 papers, 2019 to 2025). A tooth disease characterized by failure to develop one or more missing teeth. "Mutations in genes such as PAX9, MSX1, and BMP4 have been associated with tooth agenesis, abnormal dental development, and ectopic eruption patterns." (PMID 40625479, 2025). "Various BMP4 variants have been reported in patients with tooth agenesis, amongst them the BMP4 variant p.Ala42Pro identified in our patient and a female patient and her mother with tooth agenesis." (PMID 35805171, 2022). "In addition, our previous study indicated that rs17563, rs15705 and rs317250 of BMP4 were also associated with non-syndromic tooth agenesis." (PMID 32973563, 2020). "The polymorphism of BMP4 was found to be associated with tooth agenesis in human." (PMID 30683673, 2019). "However, the roles of plenty of other odontogenic genes which have been reported to be associated with tooth agenesis such as SATB2, BMP4, GREMLIN2, LRP6 and the mechanism of decreased function of hDPSCs in patients with tooth agenesis is still not fully understood." (PMID 34863303, 2021).
Alzheimer disease (5 papers, 2017 to 2021). A progressive, neurodegenerative disease characterized by loss of function and death of nerve cells in several areas of the brain leading to loss of cognitive function such as memory and language. "In addition, BMP4 overexpression did not change the protein level of APP at 1 month and 3 months of age of transgenic mice, indicating that BMP4 overexpression-induced Alzheimer’s disease needs a progressive process." (PMID 33723239, 2021). "BMP4 has indicated its key role in neurogenesis of Alzheimer’s disease models through downregulation of neurogenesis in the dentate gyrus but has not been studied in the PFC where our observed increased expression in aging may indicate its ability to play a compensatory role." (PMID 34379632, 2021).
Arthritis (5 papers, 2019 to 2024). Inflammation of a joint. "In addition, it is important to note that from our in-silico analysis, we have identified 38 BMP family members; however, we only focused on four genes, namely, BMP2a, BMP4, BMP6, and BMP7b, in a gut inflammation-associated arthritis gene expression study." (PMID 36500396, 2022). "Besides, bone morphogenetic proteins (BMPs, e.g., BMP2 and BMP4), potent mediators for osteoblast differentiation, were strongly over-expressed in the tissues from MBL−/− arthritis mice compared to those from WT counterparts." (PMID 31214191, 2019).
Hydroureter (5 papers, 2012 to 2022). The distention of the ureter with urine. "Bmp7 deficiency caused renal dysplasia and hydroureter phenotype,while Bmp4 heterozygous mutants exhibit multiple defects in urinary system, which is similar with human congenital anomalies of the kidney and urinary tract CAKUT." (PMID 22485132, 2012). "The Bmp4 heterozygote mice display severe hydroureter and kidney hypoplasia with poorly differentiated ureteral smooth muscles." (PMID 22860096, 2012). "The m6A levels of BMP4, TBX18 and SOX2 mRNAs were lower in the ureter samples from patients with megaureter (M group) than those from patients with VUR (V group)." (PMID 35795641, 2022).
hypospadias (5 papers, 2020 to 2025). Hypospadias is the displacement of the urethral meatus on the ventrum of the penis. "INO80 encodes a chromatin remodelling factor that regulates Bone Morphogenetic Protein 4 (BMP4) expression, a well-established gene involved in urethral development and hypospadias pathogenesis." (PMID 41300791, 2025). "The results show decreased expressions of Shh, Bmp4, Fgf8, Fgf10 and Fgfr2 in the genital tubercle in male rats with hypospadias." (PMID 39728417, 2024). "For instance, if genes such as INO80 and BMP4 are involved in the pathogenesis of hypospadias, therapeutic strategies that target chromatin remodelling or BMP4 signalling could be explored." (PMID 41300791, 2025). "Mutation of BMP4 and BMP7—two factors that play a role in normal urethra development, along with HOXA4 and HOXB6, were identified in Chinese patients with hypospadias, but without a clear association." (PMID 37238140, 2023).
liver fibrosis (5 papers, 2014 to 2021). "For instance, ERK1 upregulation during dimethynitrosamine induced-hepatic fibrosis is associated with induction of BMP4, together with TGF-β and PDGF, which was inhibited with AdshERK1 treatment that reverses EMT." (PMID 29295498, 2017). "Thereby, BMP4 exerts a profibrotic role in liver during bile duct ligation-induced liver fibrosis in rats through activation of Smad1 and ERK-MAPKs in HSCs." (PMID 29295498, 2017). "In the current study, the Hh-related genes, including Bmp4, Gas1, Gli3, Hhip, Ihh, Prkacb, Stk36, Wnt6, Wnt10b, Wnt9a and Wnt11, were dysregulated in our murine model of CCl4-induced liver fibrosis." (PMID 27322257, 2016).
malignant glioma (5 papers, 2014 to 2022). A grade III or grade IV glioma arising from the central nervous system. "In this review, we have discussed the recent discoveries elucidating the role of BMP4 signal pathways in malignant gliomas and reviewed innovative biocompatible materials for BMP4 delivery and their prospects for clinical applications." (PMID 32102285, 2020). "Recent advances in understanding both adult and pediatric malignant gliomas highlight critical roles of BMP4 signaling pathways in the regulation of tumor biology, and indicates its potential as a therapeutic molecule." (PMID 32102285, 2020). "In addition, BMP4 was able to abolish cancer stem cell populations in human cancers, including malignant gliomas." (PMID 36778912, 2022). "Collectively, this study suggested that hNSCs-BMP4 may help in developing therapeutic approaches for the treatment of human malignant gliomas." (PMID 26908439, 2016). "Bone morphogenetic protein 4 (BMP4) can abolish cancer stem cell populations in human cancers, including in malignant gliomas." (PMID 32102285, 2020). "After NHAs-RFP, NSCs-RFP and NSCs-BMP4-RFP were injected into the hemisphere directly contralateral to the GSC-GFP injection site for 14 days, we observed specific and appreciable engraftments of NSCs-BMP4-RFP and NSCs-RFP into malignant glioma." (PMID 26908439, 2016). "Together these data highlight a novel crosstalk between mGluR3 and BMP4 and suggest that mGlu3 receptor blockade may be combined with BMP delivery as a strategy for the treatment of malignant gliomas." (PMID 24877113, 2014).
Osteopenia (5 papers, 2020 to 2023). Osteopenia is a term to define bone density that is not normal but also not as low as osteoporosis. "An opposite animal model, mice with overexpression of Bmp4 in osteoblasts developed osteopenia due to the increased osteoclastogenesis, implicating mutual influence between main bone cell types." (PMID 35558080, 2022). "Mice with osteoblast-specific overexpression of BMP-4 have been shown to develop severe osteopenia due to increased numbers of osteoclasts, whereas mice overexpressing Noggin, a BMP-4 antagonist, have shown increased bone volume due to reduced numbers of osteoclasts." (PMID 38047271, 2023). "Our hypothesis could be confirmed by a previous study that showed overexpression of BMP-4 in bone induced severe osteopenia with increasing osteoclast number and phosphorylated Smads 1/5/8 BMP signaling in mice." (PMID 36196149, 2022). "Additionally, mice overexpressing BMP4 developed osteopenia due to the increased osteoclast number." (PMID 35558080, 2022).
prostate tumor (5 papers, 2015 to 2022). "In prostate tumours, the Sostdc1 promoter was hypermethylated in prostate tumours, leading to the suppression of hepcidin secretion due to attenuation of BMP4/7-mediated Smad phosphorylation, resulting in inhibition of cell survival." (PMID 36338475, 2022). "A recent study found that activation of BMP4-SMAD7 suppressed breast cancer metastasis, where another study supported BMP4 as a promoter of prostate tumor growth in bone through osteogenesis." (PMID 34745928, 2021).
renal fibrosis (5 papers, 2014 to 2025). A final common manifestation of a wide variety of chronic kidney diseases characterized by glomerulosclerosis and tubulointerstitial fibrosis. "Upregulation of FSP1, Col1a1, and Vim has been implicated in renal fibrosis and the downregulation of the antifibrotic BMP4 and BMP7 confirmed the fibrosis establishment, while central role of TGF-β in human and experimental models for renal fibrosis has been well described." (PMID 24995284, 2014). "In addition, we also demonstrate upregulation of fibronectin, TGF-β1, and BMP4 in the kidney, suggesting that melamine intake may trigger the development of renal fibrosis." (PMID 27324576, 2016). "Additionally, BMP4 (AlphaFold) was selected to screen the active ingredients of RRP, CO, MC, RD and PC, which have the potential to improve renal fibrosis." (PMID 41323135, 2025).
squamous cell carcinoma (5 papers, 2011 to 2022). A carcinoma arising from squamous epithelial cells. "Different patterns of BMP4 protein expression were shown in multiple tumor samples, with exceptionally strong granular BMP4 immunostaining observed in tissue samples of squamous cell carcinomas." (PMID 35694408, 2022). "In contrast, no prognostic significance was seen in FSTL1, BMP4, and Smad4 IHC expression in squamous cell carcinoma." (PMID 28852126, 2017).
acute myeloid leukemia (4 papers, 2016 to 2025). Acute myeloid leukemia (AML) is a group of neoplasms arising from precursor cells committed to the myeloid cell-line differentiation. "Notably, BMP2 and BMP4 are overexpressed in the bone marrow of Acute Myeloid Leukemia (AML) patients, supporting the aggressive clonal malignancy through excessive proliferation of immature cells blocked in their differentiation process." (PMID 35047500, 2021).
chondrosarcoma (4 papers, 2012 to 2025). A malignant cartilaginous matrix-producing mesenchymal neoplasm arising from the bone and soft tissue. "The results suggested that intrinsically BMP4 was more potent than BMP2 at 10-20 ng/ml in SW 1353 chondrosarcoma cells." (PMID 31326745, 2019).
colorectal tumors (4 papers, 2014 to 2024). "Through the online database, we identified that the expression of BMP4 was significantly high in colorectal tumor." (PMID 37370018, 2023). "This is in conflict with the report that BMP4 has antitumor activity based on the induction of differentiation, apoptosis and chemosensitization of proposed CD133+ stem cells present in human colorectal tumors." (PMID 38684650, 2024). "Indeed, exogenous administration of BMP4 to immunocompromised mice with tumors, which arose from colon CSCs, increased the antitumor effects of 5-fluorouracil and oxaliplatin, confirming that BMP4 might be developed as a therapeutic agent against cancer stem cells in advanced colorectal tumors." (PMID 24527460, 2014). "A previous study showed that the BMP-4 induces differentiation of cancer stem cells in colorectal tumor and increases their response to chemotherapy in mice, suggesting that BMP-4 might be developed as a therapeutic agent against cancer stem cells in advanced colorectal tumors." (PMID 24779016, 2014).
diabetic nephropathy (4 papers, 2013 to 2021). "Based on these data, the BMP4 signaling pathway plays important roles in the development of both podocyte injury and mesangial matrix expansion in diabetic nephropathy." (PMID 30158674, 2018). "In diabetic nephropathies, SCX also activates the expression of α-SMA/ACTA2 and bone morphogenetic protein 4, to promote differentiation of mesangial cells into activated myofibroblasts." (PMID 32708589, 2020).
oral carcinoma (4 papers, 2011 to 2024). "Therefore, understanding the cellular mechanisms of BMP4-mediated regulation of self-renewal and differentiation of oral-SLCCs and its potential use as differentiating agent may lead to innovative interventions against gingivobuccal oral cancers." (PMID 30287850, 2018). "Overall, our data clearly demonstrated the determining role of BMP4 in exerting the suppressive effect of C1-type CAFs in oral cancer cells stemness, whereas proliferative effect was found to be independent of BMP4." (PMID 30287850, 2018).
orofacial cleft (4 papers, 2012 to 2025). A disorder of facial skeleton that is characterized by cleft lip and/or cleft palate that result in feeding, speech and hearing problems caused by failures during development. "BMP4 has been shown to regulate mammalian palatogenesis and has been reported to be associated with orofacial clefting in humans." (PMID 23044548, 2012). "Thus, further genetic association studies designed to examine these two conditions separately would be helpful in elucidating the role BMP4 rs17563 in orofacial clefts." (PMID 23227324, 2012).
otosclerosis (4 papers, 2013 to 2023). Formation of spongy bone in the labyrinth capsule which can progress toward the stapes (stapedial fixation) or anteriorly toward the cochlea leading to conductive, sensorineural, or mixed hearing loss. "Bone morphogenetic proteins 2 and 4 (BMP2 and BMP4), which are members of the TGFB superfamily and play important roles in several stages of bone metabolism, have also been associated with otosclerosis susceptibility." (PMID 37647735, 2023). "A study investigating rare and common variations in BMP2 and BMP4 did not identify an association between common variants and otosclerosis." (PMID 37647735, 2023). "Various members of this family including TGF-β1 and bone morphogenetic proteins BMP2 and BMP4 have been associated with otosclerosis in some candidate gene association studies but not all; however, a precise role for this gene family in development of otosclerosis has not been defined." (PMID 27056980, 2016). "It has been reported that COL1A1, BMP2, BMP4, TGFB1, and RELN genes may also contribute to the development of otosclerosis." (PMID 23864959, 2013).
periodontitis (4 papers, 2021 to 2026). An acute or chronic inflammatory process that affects the tissues that surround and support the teeth. "The previous study elucidated that the C-reactive protein (CRP)/bone morphogenetic protein 4 (BMP4) signaling pathway mediates periodontitis-associated anxiety-like behaviors in rats." (PMID 42318640, 2026). "In this study, the effect of several combinations of active substances in LD and ULD was analyzed in an in vitro model of periodontitis, the same as that previously used when we assessed the effect of the unitary MIM BMP-4." (PMID 37445663, 2023). "Gingival BMP-2 and BMP-4 levels were similar in acromegaly and control groups in general, with and without chronic periodontitis." (PMID 33421969, 2021). "Gingival BMP-4 levels were similar in those with and without periodontitis." (PMID 33421969, 2021). "In addition, it is important to consider the previous work on the action of BMP-4 (5 CH), which is one of the active substances listed in MIM-seq composition, and it was able to increase collagen deposition and reduce PGE2 release in the same in vitro model of periodontitis." (PMID 37445663, 2023). "When the acromegalics and healthy controls with and without chronic periodontitis were analysed separately, both the acromegalics and the healthy control group, revealed similar gingival BMP-2 and BMP-4 levels." (PMID 33421969, 2021).